CIC (capicua transcriptional repressor)
Diseases named in the same sentence as CIC in open-access papers (continued):
Sharing a sentence is not in itself a finding about the gene and the disease.
cancer (34 papers, 2012 to 2026). A tumor composed of atypical neoplastic, often pleomorphic cells that invade other tissues. "EGFR, IDH1, ARID1A, and CIC also displayed two associations each, while the remaining 68 hotspots corresponded to one gene associated with one specific cancer type." (PMID 38473427, 2024). "It is worth underlining that CiC expression is increased in cancer cells, in which high levels of acetyl-CoA are required for both lipid synthesis and histone acetylation." (PMID 27231907, 2016). "Human CIC is frequently mutated in samples from cancer genome studies such as The Cancer Genomic Atlas (TCGA)." (PMID 26683696, 2015). "CIC is a transcriptional repressor implicated in various cancers, and its mutation could disrupt gene expression control." (PMID 40406258, 2025). "CIC mutations correlate with a more malignant subtype in a variety of cancers, including ODGs." (PMID 36647117, 2023). "Mutations and loss of CIC have been reported to promote the progression of various cancers via derepression of cancer-associated CIC target genes, including polyomavirus enhancer activator 3 (PEA3) group genes (ETS variant transcription factor 1 [ETV1], ETV4, and ETV5)." (PMID 36619173, 2022). "First, dozens of mutations in CIC have been identified in patients with various types of cancers." (PMID 26124181, 2015). "CIC, the protein encoded by the CIC gene, has been shown to play a multitude of roles in both normal and cancer cell functions; however, most studies exploring these roles focus on a single aspect of CIC function and may therefore overlook complex interconnected activities in which CIC is involved." (PMID 37345142, 2023). "First, the subinteractomes of these ORF proteins contain proteins associated with ‘cancer hallmark’ and oncoproteins (e.g., the case of C5orf24 and its protein partners XPO1, PBX1, MYC, CIC, GOPC, CREB1 and STK11)." (PMID 37373333, 2023). "Among them, ARID1A, TSC2, JAK3, CIC, CINNB1, and SETD2 were mutated at the early stage of carcinogenesis, which played an essential role in advancing early cancer development and progression." (PMID 35795211, 2022). "Despite the findings supporting the potential role of CIC in cancer, it has not been clear whether CIC deficiency or mutations indeed contribute to cancer progression." (PMID 26124181, 2015). "Investigation into the molecular function of CIC in cancer and GBM in particular, is further merited by recent findings connecting CIC’s downstream target ETV1 in GBM14." (PMID 30737375, 2019). "Here we report that Capicua (CIC), an HMG-box transcriptional repressor involved in Ras/MAPK signaling and cancer progression, employs an additional distinct mode of DNA binding that enables selective recognition of its targets." (PMID 28278156, 2017).
CNS tumors (3 papers, 2024). "Our study reveals that pediatric CNS tumors harboring the CIC::LEUTX fusion represent a heterogeneous set of tumors." (PMID 38926750, 2024).
neurodevelopmental disorder (2 papers, 2024 to 2025). A behavioral and cognitive disorder with onset during the developmental period that involves impaired or aberrant development of intellectual, motor, or social functions. "In human subjects, the presence of heterozygous truncating mutations in CIC frequently gives rise to ASD and other neurodevelopmental disorders, thereby indicating that abnormalities within the ATXN1-CIC pathway may constitute a pathogenic pathway for ASD." (PMID 41160232, 2025).
CIC also shares sentences with these, for which no sentence is quoted: brain tumors (3 papers); breast carcinoma (3); cutaneous melanoma (2); ganglioglioma (2); gastric cancer (2); metastatic disease (2); oligoastrocytoma (2); thalassemia (2); acral melanomas (1); adenoid cystic carcinoma (1); Alpha-thalassemia (1); anaplastic oligoastrocytoma (1); B-cell lymphoma (1); bladder urothelial carcinoma (1); bone tumor (1); clear cell sarcoma (1); colon cancer (1); connective tissue tumors (1); diffuse astrocytoma (1); epithelial-myoepithelial carcinoma (1); fragile X syndrome (1); glioneuronal tumors (1); head and neck squamous cell carcinoma (1); lymphedema (1); malignant glioma (1); malignant lymphomas (1); mucoepidermoid carcinoma (1); non-alcoholic steatohepatitis (1); non-small cell lung carcinoma (1); Obesity (1).
A further 11 diseases each share a sentence with CIC in 1 paper.